ENSG00000284732 (novel olfactory receptor)
Gene: Protein-coding gene on chromosome 11 (56,459,221 to 56,473,352, reverse strand). Ensembl gene ENSG00000284732.
Genetic constraint (gnomAD): Loss-of-function variants: 4 observed, 4.51 expected, observed/expected ratio (o/e) 0.89, 90% interval 0.43 to 1.77. That is too few expected variants to judge how well the gene tolerates losing a copy. Missense variants: 507 observed, 451.89 expected, observed/expected ratio (o/e) 1.12, 90% interval 1.04 to 1.21. Synonymous variants: 192 observed, 164.51 expected, observed/expected ratio (o/e) 1.17, 90% interval 1.04 to 1.32.